MAPK3 (mitogen-activated protein kinase 3)
Description:
Serine/threonine kinase which acts as an essential component of the MAP kinase signal transduction pathway. MAPK1/ERK2 and MAPK3/ERK1 are the 2 MAPKs which play an important role in the MAPK/ERK cascade. They participate also in a signaling cascade initiated by activated KIT and KITLG/SCF. Depending on the cellular context, the MAPK/ERK cascade mediates diverse biological functions such as cell growth, adhesion, survival and differentiation through the regulation of transcription, translation, cytoskeletal rearrangements. The MAPK/ERK cascade also plays a role in initiation and regulation of meiosis, mitosis, and postmitotic functions in differentiated cells by phosphorylating a number of transcription factors. About 160 substrates have already been discovered for ERKs. Many of these substrates are localized in the nucleus, and seem to participate in the regulation of transcription upon stimulation. However, other substrates are found in the cytosol as well as in other cellular organelles, and those are responsible for processes such as translation, mitosis and apoptosis. Moreover, the MAPK/ERK cascade is also involved in the regulation of the endosomal dynamics, including lysosome processing and endosome cycling through the perinuclear recycling compartment (PNRC); as well as in the fragmentation of the Golgi apparatus during mitosis. The substrates include transcription factors (such as ATF2, BCL6, ELK1, ERF, FOS, HSF4 or SPZ1), cytoskeletal elements (such as CANX, CTTN, GJA1, MAP2, MAPT, PXN, SORBS3 or STMN1), regulators of apoptosis (such as BAD, BTG2, CASP9, DAPK1, IER3, MCL1 or PPARG), regulators of translation (such as EIF4EBP1) and a variety of other signaling-related molecules (like ARHGEF2, DEPTOR, FRS2 or GRB10). Protein kinases (such as RAF1, RPS6KA1/RSK1, RPS6KA3/RSK2, RPS6KA2/RSK3, RPS6KA6/RSK4, SYK, MKNK1/MNK1, MKNK2/MNK2, RPS6KA5/MSK1, RPS6KA4/MSK2, MAPKAPK3 or MAPKAPK5) and phosphatases (such as DUSP1, DUSP4, DUSP6 or DUSP16) are other substrates which enable the propagation the MAPK/ERK signal to additional cytosolic and nuclear targets, thereby extending the specificity of the cascade. Phosphorylates GJA1 at 'Ser-279' and 'Ser-282' resulting in an increase in GJA1 ubiquitination and ultimately lysosomal degradation (By similarity).
Synonyms: ERK-1; p44-MAPK; ERK1; PRKM3; p44mapk; p44erk1; ERT2; HS44KDAP; HUMKER1A; p44-ERK1
Tractability: Small molecule: a drug acting on it is in phase 2 or 3 trials; a structure with a bound ligand is known; a high-quality ligand is known; it belongs to a druggable protein family. Antibody: its Gene Ontology location is reachable by antibodies, with medium confidence. PROTAC: it is named in the literature on targeted protein degradation; UniProt records ubiquitination sites on it; ubiquitination databases record sites on it; its protein half-life has been measured; a small molecule that binds it is known.
Target class: CMGC protein kinase ERK subfamily; CMGC protein kinase group; CMGC protein kinase MAPK family; Enzyme; Kinase; Protein Kinase
Chemical probes: ERKi (high quality), SCH772984 (high quality), ulixertinib
Safety:
Unwanted effects reported when the protein is acted on. In parentheses: how it was acted on, where the effect was seen, and who reports it.
heart disease (cardiovascular system; source: Force et al. (2011))
Gene: Protein-coding gene on chromosome 16 (30,114,105 to 30,123,506, reverse strand). Ensembl gene ENSG00000102882.
Subcellular location: Cytoplasm; Nucleus; Membrane, caveola; Cell junction, focal adhesion
Subcellular location (Human Protein Atlas): Nucleoplasm; Basal body; Cytosol; Microtubules; Primary cilium; Primary cilium tip
Pathways (Reactome):
Signal Transduction: Downregulation of SMAD2/3:SMAD4 transcriptional activity; ERK/MAPK targets; ERKs are inactivated; ESR-mediated signaling; Estrogen-dependent nuclear events downstream of ESR-membrane signaling; Frs2-mediated activation; Gastrin-CREB signalling pathway via PKC and MAPK; MAP2K and MAPK activation; MAPK3 (ERK1) activation; Negative feedback regulation of MAPK pathway; Negative regulation of FGFR1 signaling; Negative regulation of FGFR2 signaling; Negative regulation of FGFR3 signaling; Negative regulation of FGFR4 signaling; Negative regulation of MAPK pathway; PI5P, PP2A and IER3 Regulate PI3K/AKT Signaling; RAF-independent MAPK1/3 activation; RAF/MAP kinase cascade; RHO GTPases Activate NADPH Oxidases; RHO GTPases Activate WASPs and WAVEs; Regulation of PTEN gene transcription; SMAD2/SMAD3:SMAD4 heterotrimer regulates transcription; Signal attenuation; Signaling by Activin; Spry regulation of FGF signaling
Disease: FCGR3A-mediated phagocytosis; Nuclear events stimulated by ALK signaling in cancer; Paradoxical activation of RAF signaling by kinase inactive BRAF; Signaling by BRAF and RAF1 fusions; Signaling by LTK in cancer; Signaling by MAP2K mutants; Signaling by RAF1 mutants; Signaling by high-kinase activity BRAF mutants; Signaling by moderate kinase activity BRAF mutants; Signaling downstream of RAS mutants; Suppression of apoptosis
Immune System: Activation of the AP-1 family of transcription factors; Advanced glycosylation endproduct receptor signaling; FCERI mediated MAPK activation; Growth hormone receptor signaling
and 20 more pathways
Gene Ontology:
Molecular function: DNA-binding transcription factor binding; identical protein binding; MAP kinase activity; phosphatase binding; protein binding; protein serine kinase activity; protein serine/threonine kinase activity; ATP binding; phosphotyrosine residue binding; protein kinase activity
Biological process: BMP signaling pathway; cellular response to amino acid starvation; cellular response to mechanical stimulus; epidermal growth factor receptor signaling pathway; interleukin-1-mediated signaling pathway; interleukin-34-mediated signaling pathway; MAPK cascade; negative regulation of T cell mediated immune response to tumor cell; negative regulation of TORC1 signaling; peptidyl-tyrosine autophosphorylation; phosphorylation; positive regulation of cyclase activity; positive regulation of ERK1 and ERK2 cascade; positive regulation of macrophage chemotaxis; positive regulation of macrophage proliferation; positive regulation of neuroinflammatory response; positive regulation of telomere maintenance; positive regulation of transcription by RNA polymerase II; protein phosphorylation; response to epidermal growth factor; signal transduction in response to DNA damage; stress-activated MAPK cascade; caveolin-mediated endocytosis; cell surface receptor signaling pathway; ERK1 and ERK2 cascade; and 13 more
Cellular component: cytoplasm; nuclear envelope; nucleoplasm; caveola; cytoskeleton; cytosol; early endosome; endoplasmic reticulum lumen; focal adhesion; Golgi apparatus; late endosome; mitochondrion; nucleus; plasma membrane; glutamatergic synapse; pseudopodium
Genetic constraint (gnomAD): Loss-of-function variants: 27 observed, 39.81 expected, observed/expected ratio (o/e) 0.68, 90% interval 0.5 to 0.94. The upper end of that interval is the gene's LOEUF score, 0.94, which puts it in group 3 of 6, group 1 being the genes least tolerant of losing a copy. Missense variants: 365 observed, 486.94 expected, observed/expected ratio (o/e) 0.75, 90% interval 0.69 to 0.82. Synonymous variants: 197 observed, 201.65 expected, observed/expected ratio (o/e) 0.98, 90% interval 0.87 to 1.1.
Homologues: Orthologues: chimpanzee MAPK3 (100% identical), macaque MAPK3 (99% identical), pig MAPK3 (97% identical), rat Mapk3 (97% identical), mouse Mapk3 (97% identical), guinea pig MAPK3 (96% identical), dog MAPK3 (87% identical), rabbit MAPK3 (86% identical), zebrafish mapk3 (84% identical), Caenorhabditis elegans pmk-1 (40% identical), Caenorhabditis elegans pmk-2 (38% identical), Drosophila melanogaster nmo (37% identical), and 8 more. Paralogues in human: MAPK1 (82% identical), MAPK7 (48% identical), MAPK14 (43% identical), MAPK11 (41% identical), MAPK6 (41% identical), MAPK13 (39% identical), NLK (38% identical), MAPK12 (38% identical), MAPK10 (38% identical), MAPK9 (38% identical), MAPK4 (37% identical), MAPK8 (37% identical), and 7 more.
Diseases named in the same sentence as MAPK3 in open-access papers:
MAPK3 is named in the same sentence as 794 diseases in open-access papers, as found by Europe PMC text mining. Sharing a sentence is not in itself a finding about the gene and the disease. The quoted sentences say what the papers report.
breast cancer (836 papers, 2004 to 2026). A primary or metastatic malignant neoplasm involving the breast. "On the other hand, high levels of CDH1/E-cadherin and MAPK3/ERK1 have been associated with favorable prognoses in breast cancer, and Rsv increases their levels and/or activity in MCF7 cells." (PMID 33204396, 2020). "Elevated expression and/or activity of MAPK3 is linked to the onset, development, drug resistance, and metastasis of various carcinomas such as ovarian cancer, glioma, lung cancer, and breast cancer." (PMID 37090055, 2023). "Interestingly, many of these same genes, including MAPK3, are also associated with breast cancer risk." (PMID 28595647, 2017). "Finally, a SNP in MAPK3 (rs78564187) was associated with ER− breast cancer, OR equal to 1.26 (P=3.7×10−4) per high-risk allele." (PMID 27942580, 2016). "Three essential core genes—EGFR, BCL2, and MAPK3—in the PPI network of breast cancer-related targets of SP were among the top ten genes." (PMID 39057437, 2024). "Extensive research studies have investigated both MAPK1 and MAPK3 as potential therapeutic targets for various types of cancers, including breast cancer." (PMID 38794187, 2024). "Five proteins (i.e., EGFR, MAPK3, ESR1, MAPK1, and PTGS2) associated with breast cancer were selected as receptor proteins." (PMID 38794187, 2024). "It has been identified that microRNA-143 is able to target MAPK3 to control bone metastasis and proliferation in breast cancer cells." (PMID 34126594, 2021). "The regulation of the expression of EGF and its downstream genes in the MAPK pathway, such as RRAS and MAPK3, have also been described as important inhibitors of apoptosis on breast cancer cells induced by chemotherapeutic agents." (PMID 30173296, 2018). "BAIAP2 was associated with overall and ER+ breast cancer; CALM2 with overall breast cancer; CSNK2A1 with ER+ breast cancer; and BRAF, BAD, and MAPK3 with ER− breast cancer." (PMID 27942580, 2016). "The most significant gene associations (P⩽0.01) were BAIAP2 and CALM2 for overall breast cancer; BAIAP2 and CSNK2A1 for ER+ breast cancer; and BRAF, BAD, and MAPK3 for ER− breast cancer." (PMID 27942580, 2016). "This co-targeting approach is particularly promising in tumors where both MAPK and PI3K pathways are activated.​ These findings underscore the importance of MAPK3 activation in breast cancer progression and the potential for MAPK pathway inhibitors like trametinib as viable treatment options." (PMID 39850811, 2024). "The decision to test MAPK1/ERK2 only in the RT-PCR assays was based on reports that show MAPK3/ERK1 association with a better prognosis and its role in modulating the YAP1 signaling pathway, indicating that MAPK3 is a negative regulator of breast cancer development." (PMID 33707603, 2021). "MAPK3’s involvement in cell proliferation and survival, alongside PIK3CA and mTOR’s roles in metabolic regulation and tumor progression, underlines their contribution to breast cancer pathophysiology, particularly in aggressive subtypes like TNBC and HER2-positive cancers." (PMID 39850811, 2024). "Furthermore, our microarray analysis of the profile of genes related to the PI3K/AKT/mTOR pathway and the miRNAs involved in regulating their expression indicated that also the MAPK3 gene plays an important role in the cascade in question in the context of breast cancer." (PMID 39850811, 2024).
breast cancer (continued). "Among them, EGFR, MAPK1, MAPK3, PTGS2, and ESR1 were specifically evaluated for breast cancer treatment." (PMID 38794187, 2024). "Similarly, a number of earlier investigations have demonstrated that MAPK3 expression may be a possible prognostic indicator of reduced survival in patients with malignant tumors, including breast cancer, oral squamous cell carcinoma, and prostate cancer are associated with MAPK1/3." (PMID 38800011, 2024). "Here, we present a list of seven putative genes that are modulated by Rsv in breast cancer in the context of cotreatment with Doxo: HSP90AA1, CCND1, CDH1, ESR1, MAPK3, PTPN11, and RPS6KB1." (PMID 33204396, 2020). "Specifically, the identification of miRNAs such as miR-129, miR-19a-3p, and miR-30d-5p, as well as proteins like COL4A1, MAPK3, PIK3CG, and mTOR, provides valuable insights into the molecular mechanisms underpinning aggressive breast cancer subtypes, such as TNBC." (PMID 39850811, 2024). "We showed that miR-190a-3p, a key regulator of gene expression and pathways important in breast cancer, is potentially involved in the regulation of COL4A1, MAPK3, PIK3CG, and PIK3R1, all of which are integral to pathways associated with breast cancer progression." (PMID 39850811, 2024). "SRPK1 silencing results in increased rates of apoptosis, and decreased phosphorylation of mitogen-activated protein kinase 3 (MAPK3), MAPK1 and protein kinase B (AKT) in breast cancer cell lines, suggesting a likely relationship between SRPK1 and AKT/MAPK signalling pathways." (PMID 35583632, 2022). "Also, 7 genes (CTGF, ESR1, MAPK3, PIK3R3, PLAU, PRNP, and RET) were reported to be highly relevant to growth (P<1E-04) and microtubule dynamics (P<4E-05) in tumor cell lines, and apoptosis in breast cancers (P<1E-04)." (PMID 23185353, 2012). "The Kaplan-Meier plotter was used to investigate the expression of ERK1 (MAPK3) and ERK2 (MAPK1) across breast cancer samples from all breast cancer patients (not stratified by disease subtype)." (PMID 32444778, 2020).
melanoma (448 papers, 2005 to 2026). A malignant, usually aggressive tumor composed of atypical, neoplastic melanocytes. "The findings revealed that three Nitroglycerin genes (EGFR, HRAS and MAPK3) were found to be common in 4 types of cancers viz Bladder cancer, Endometrial cancer, Melanoma and Non-small cell lung cancer." (PMID 34764329, 2021). "A study using melanoma cells has shown that the MAPK3/1 pathway phosphorylates STK11 on Ser325 and Ser428 and promotes the uncoupling of AMPK from STK11, which negatively regulates AMPK." (PMID 20808308, 2010). "A network reconstructed from the selected functions shows a strong integration with the functions involved in colon cancer and melanoma, namely AKT1, EGFR and MAPK3." (PMID 37629086, 2023). "For example, we found that the differential expression of the MAPK3 gene stratified melanoma cell lines into Cladribine responders and non-responders, which is consistent with what is known about the mechanism of action of Cladribine." (PMID 29435161, 2018). "In LN, MAPK3 (cf = 53), PIK3R1 (cf = 51), HRAS (cf = 46), PIK3R2 (cf = 45) and KRAS (cf = 44) are the top 5 cross-talk genes, and as expected most of these are already recognized melanoma markers." (PMID 26558755, 2015).
lung carcinoma (290 papers, 2004 to 2026). "Previous studies discussed PRMT5′s role in modulating the activity of ERK in glioblastoma neurospheres and lung cancer, with ERK being encoded by the MAPK3 gene." (PMID 38666828, 2024). "Hyperphosphorylation at MAPK3 is reported to induce cisplatin resistance in lung cancer cells." (PMID 29556515, 2018). "In brief, preclinical evidence reveals that targeting IL-6, STAT3, MAPK3, or AKT1 provides an effective way to suppress lung cancer." (PMID 39258670, 2024). "Analysis of human lung cancer data sets derived from The Cancer Genome Atlas (TCGA) showed that KRAS, RAF1, MAP2K1, MAP2K2, MAPK3, and MAPK1 expression levels were positively correlated with the BCL6 expression level." (PMID 36377663, 2022). "Fortunately, we obtained four hub genes (MAPK3, MOV10, XAB2, and POLR2A), which potentially interact with BCAR1 and play carcinogenetic roles in lung cancer." (PMID 33001583, 2020).
prostate carcinoma (239 papers, 2005 to 2026). A carcinoma that arises from epithelial cells of the prostate gland. "MAPK1 and MAPK3 have been reported to be associated with various types of cancer, such as prostate cancer, colorectal cancer and gastric cancer." (PMID 29282071, 2017). "In particular, EGFR, MAPK3, and MAPK1 are involved in the HIF-1, estrogen, FoxO, and Rap1 signaling pathways as well as in central carbon metabolism in cancer, prostate cancer, focal adhesion, and gap junction pathways." (PMID 36430946, 2022). "KS6A2/RPS6KA2, also known as RSK/RSK3, is a member of the RSK serine/threonine-protein kinase family that acts as a downstream effector of ERK in the MAPK1/ERK2 and MAPK3/ERK1 signaling pathway, mediating cellular proliferation and survival in prostate cancer." (PMID 34359681, 2021). "Three genes closely related to AR functions in prostate cancer, AR, KLK3 and MAPK3, are among the detected DE genes." (PMID 30367578, 2018).
gastric cancer (225 papers, 2007 to 2026). A primary or metastatic malignant neoplasm involving the stomach. "Among the differentially expressed NRGs, PROCR and MAPK3 showed highest copy number loss frequency in stage I and stage II gastric cancer patients." (PMID 38221932, 2024). "The overexpression and/or hyperactivity of MAPK3 has been linked to the initiation, development, cancer cell migration, and drug resistance in various carcinomas, including liver, thyroid, lung, and gastric cancers." (PMID 37090055, 2023). "Key metabolites such as linoleic acid, panaxynol, methyl linoleate, palmitoleic acid, and oleic acid have been identified to interact with critical targets in gastric cancer, including EGFR, MAPK1, MAPK3, and IL-6, significantly inhibiting the proliferation of gastric cancer cells." (PMID 39193331, 2024). "In addition, up-regulation of miR-206 can decrease DDP resistance in gastric cancer cells via the inhibition of MAPK3 expression." (PMID 34746018, 2021). "Dysfunction of Wnt signals with consequently abnormal activation of MAPK3 pathways was found in colorectal cancer (CRC) and gastric cancer (GC)." (PMID 34671555, 2021). "Several studies have shown that the tumour growth of gastric cancer could be restrained by inhibiting the expression level of MAPK1 and MAPK3." (PMID 36299773, 2022). "MAPK3 is an important signal transduction molecule in the ERK/MAPK pathway, and previous studies have found that the enhanced functional activity of MAPK3 plays a critical role in the development and progression of gastric cancer." (PMID 33194668, 2020).